HYDIN (HYDIN axonemal central pair apparatus protein)
Diseases named in the same sentence as HYDIN in open-access papers:
HYDIN is named in the same sentence as 27 diseases in open-access papers, as found by Europe PMC text mining. Sharing a sentence is not in itself a finding about the gene and the disease. The quoted sentences say what the papers report.
Hydrocephalus (7 papers, 2011 to 2024). Hydrocephalus is an active distension of the ventricular system of the brain resulting from inadequate passage of CSF from its point of production within the cerebral ventricles to its point of absorption into the systemic circulation. "The HYDIN gene was first described in mice as a recessive cause of hydrocephalus, with its expression localised to the motile cilia." (PMID 38605126, 2024). "In mice, an autosomal recessive mutation in HYDIN (hydrocephalus-inducing [Ensembl:ENSMUSG00000059854]) causes a lethal form of a communicating hydrocephalus with a perinatal onset." (PMID 26452345, 2015). "It was postulated that HYDIN2 might contribute to the reciprocal macrocephaly/microcephaly phenotype, because mutation of the ancestral HYDIN gene leads to hydrocephalus in mouse." (PMID 28279197, 2017). "Loss or gain of HYDIN2 has been hypothesized to underlie these head circumference phenotypes in light of its expression in brain, its inclusion in the typical rearrangement interval, and the association of homozygous losses of HYDIN in mouse with hydrocephalus." (PMID 28279197, 2017). "The motile cilia in homozygous HYDIN mutant mice are reported to be unable to bend fully and thus have a significantly reduced cilia beat frequency, which leads to impaired fluid flow in the brain and the development of hydrocephalus." (PMID 38605126, 2024). "In humans, however, recessive mutations in HYDIN were found associated with primary ciliary dyskinesia without hydrocephalus." (PMID 28279197, 2017). "While defects in the HYDIN gene result in hydrocephalus, this genomic region has not previously been associated with WBC." (PMID 21738479, 2011).
primary ciliary dyskinesia (7 papers, 2017 to 2024). A rare, genetically heterogeneous, primarily respiratory disorder characterized by chronic upper and lower respiratory tract disease. "The WES analysis showed that a copy number loss of HYDIN existed in each of the 6 individuals with primary ciliary dyskinesia, and electron microscope scanning also confirmed that the cilia lacked in the HYDIN mutation samples." (PMID 39850822, 2024). "Mutations in the underlying genes, CFAP54 (C1d) and HYDIN (C2b), lead to symptoms associated with primary ciliary dyskinesia including sperm motility defects." (PMID 32785227, 2020). "Its expression in lung and testis is consistent with the observation that recessive mutations in HYDIN cause primary ciliary dyskinesia, with the primary phenotypes being chronic respiratory infections and male infertility in humans." (PMID 28279197, 2017). "Population studies show that HYDIN mutations can cause primary ciliary dyskinesia (PCD)." (PMID 35198563, 2021). "In this regard, we found a deleterious variant of HYDIN; this central apparatus protein is related to Primary Ciliary Dyskinesia (OMIM-P 608647, Ciliary Dyskinesia, Primary 5) but not to the randomization of the left-right body or CHD." (PMID 36140829, 2022).
Infertility (5 papers, 2022 to 2025). "To confirm the pathological manifestations associated with the HYDIN variants, we performed IF and RT-qPCR analyses of sperm samples from fertile controls and infertile patient." (PMID 36742411, 2023). "Routine semen examinations indicated that semen volume and concentration were unaffected, yet sperm motility and progressive motility decreased dramatically, suggesting that the variants of HYDIN we found may cause infertility and PCD." (PMID 36742411, 2023). "In this study, we identified two compound heterozygous HYDIN variants in two infertile patients with asthenoteratozoospermia from unrelated families and demonstrated that HYDIN deficiency causes abnormalities in sperm head, neck, and flagella morphology and ultrastructures." (PMID 36742411, 2023). "Furthermore, our findings suggest that ICSI could be recommended for patients with infertility caused by HYDIN variants." (PMID 36742411, 2023). "Among women with known genetic results, those with infertility had DNAH5, DNAAF3, ZMYND10, CCDC40, RSPH9 and HYDIN mutations." (PMID 40142748, 2025). "We identified ten infertile male individuals with pathogenic variants in CCDC39 (one) and CCDC40 (two) encoding ruler proteins, RSPH1 (two) and RSPH9 (one) encoding radial spoke head proteins, and HYDIN (two) and SPEF2 (two) encoding CP-associated proteins, respectively." (PMID 36873931, 2023).
male infertility (5 papers, 2017 to 2025). The inability of the male to effect fertilization of an ovum after a specified period of unprotected intercourse. "The male infertility-related variants identified in SPATA3, TTC21A, TERB1, HYDIN, and CCDC155 can be considered additional examples." (PMID 37644014, 2023). "We and others have reported male infertility in HYDIN-and SPEF2-mutant individuals." (PMID 36873931, 2023). "Therefore, we explored the role of HYDIN in sperm morphology and motility, as well as the relationship between HYDIN and male infertility." (PMID 36742411, 2023). "Thus, IF microscopy in sperm flagella with antibodies targeting SPEF2 can help to determine pathogenicity of DNA variants in HYDIN- and SPEF2-mutant individuals, aiding diagnosis of male infertility." (PMID 36873931, 2023).
breast carcinoma (3 papers, 2015 to 2021). "Somatic mutations in HYDIN were found in breast cancer samples." (PMID 34540650, 2021). "In addition to the observed recurrent missense mutation (T3867A) in the HYDIN gene in the present study, ten other mutations have been reported in previous studies, though each was observed only once in 100 breast cancer patients." (PMID 26870154, 2015). "In summary, we discovered novel somatic mutations in the TRPM6, HYDIN, ENTHD1 and NDUFB10 genes in early onset Chinese breast cancer patients through whole exome sequencing." (PMID 26870154, 2015).
ciliopathy (3 papers, 2022 to 2024). A genetic disorder of the cellular cilia or the cilia anchoring structures, the basal bodies, or of ciliary function. "Intriguingly, the situs solitus T180401 proband, which carries both a heterozygous compound DNAH9 variant and a HYDIN homozygous variant, did not display any observable clinical manifestation of a ciliopathy." (PMID 36140829, 2022). "Besides ARL13B and ARL3 that are involved in human Joubert syndrome, the IFT complex, HYDIN, and the ODA complex are all confirmed human ciliopathy genes." (PMID 39231220, 2024).
situs inversus (3 papers, 2022 to 2024). A congenital condition in which there is complete right-to-left reversal of the position of the major thoracic and abdominal organs (that is, they are arranged in a mirror image of the normal positioning). "No situs inversus was reported for any of the patients as is expected for individuals carrying HYDIN variants based on the lack of central pair structure in nodal cilia." (PMID 39291810, 2024). "Normal visceral placement is driven by the dynein of nodal cilia, so patients with gene mutations encoding non-dynein structural components such as RSPH1, RSPH3, and HYDIN have not been reported for situs inversus." (PMID 36583018, 2022). "Mutations in proteins (e.g., HYDIN, RSPH1) that affect the central pair, which are not present in nodal cilia, cause PCD without causing the situs abnormalities associated with PCD (e.g., situs inversus, situs ambiguous)." (PMID 35163670, 2022).
atrial septal defect (2 papers, 2024). Interauricular communication is a congenital malformation characterized by a communication between the atrial chambers of the heart. "Recent whole exome sequencing has revealed variants in HYDIN are associated with sporadic atrial septal defects." (PMID 39202712, 2024).
congenital hydrocephalus (2 papers, 2010 to 2025). Hydrocephalus that is present at birth. "HYDIN encodes an axonemal protein; mutation of HYDIN is related to congenital hydrocephalus." (PMID 21172017, 2010).
Joubert syndrome (2 papers, 2021 to 2024). Joubert syndrome (JS) is characterized by congenital malformation of the brainstem and agenesis or hypoplasia of the cerebellar vermis leading to an abnormal respiratory pattern, nystagmus, hypotonia, ataxia, and delay in achieving motor milestones. "The remaining novel variants were: CCDC39:p.Glu598* (CADD, 37); CCDC40:c.1097delT (frameshift); CEP104:p.Glu698Lys (Joubert syndrome 25, Patient 9); DNAAF5:p.Val431Ala (Condel: 0.886); DNAH5 duplication of exon 1–48 (unknown significance); HYDIN:p.Pro3213Arg (likely pathogenic, Patients 17–18)." (PMID 34768622, 2021).
lung carcinoma (2 papers, 2025). "A total of 6 genes (LYVE1, CLEC3B, FGA, AOC3, HYDIN, and HBB) exhibited differential expressions in the plasma of LUSC and the area of the lesion in lung cancer (including LUAD and LUSC)." (PMID 40496615, 2025).
melanoma (2 papers, 2023). A malignant, usually aggressive tumor composed of atypical, neoplastic melanocytes. "In an analysis of melanoma patients by gender, age, and M stage, it was found that male patients had a higher proportion of HYDIN mutations." (PMID 37595251, 2023). "In this work, we explored the correlation between HYDIN mutations and response in melanoma patients with ICIs treatment." (PMID 37595251, 2023). "The results revealed that 670 of the 10429 patients included in TCGA had mutations in HYDIN (6.42%), Notably, the highest incidence of HYDIN mutations was found in melanoma patients, with a rate of 36.14% (159/438)." (PMID 37595251, 2023). "Here, we explored the association between HYDIN mutations (HYDIN-MUT) in melanoma and ICIs efficacy." (PMID 37595251, 2023). "More importantly, the high mutation rate of HYDIN in melanoma patients (36.14%) means that more beneficiaries can be identified for precision treatment." (PMID 37595251, 2023). "Thus, we intend to systematically investigate the association between HYDIN mutations and ICIs efficacy in melanoma patients." (PMID 37595251, 2023). "We found the HYDIN mutations ranked 17th in the frequency of mutations in melanoma patients." (PMID 37595251, 2023). "There was no remarkable difference in OS between HYDIN-MUT patients and HYDIN-WT patients (HR = 0.819 [95% CI, 0.616–1.088], Plog rank = 0.167), which confirmed that HYDIN mutations can be used as potential predictive biomarkers for anti-PD-1 treatment of melanoma patients." (PMID 37595251, 2023). "HYDIN mutations successfully predict better clinical outcomes in ICIs-treated melanoma patients, indicating that HYDIN mutations could be a potential predictive biomarker for ICIs in melanoma patients." (PMID 37595251, 2023). "We found that in the total ICIs treated cohort, melanoma patients with the HYDIN-MUT had significantly higher TMB and NAL, suggesting that the HYDIN mutations were associated with higher tumor immunogenicity." (PMID 37595251, 2023).
ovarian carcinoma (2 papers, 2021 to 2024). A malignant neoplasm originating from the surface ovarian epithelium. "The decreased expression of HYDIN and other cilia-associated genes has an important role in inhibiting the formation of tubal cilia, which may promote the development of ovarian cancer." (PMID 39850822, 2024). "Therefore, we aimed to evaluate the relationship between fallopian tube ciliary loss in patients with EOC and the presence of the cilia-associated gene HYDIN, and the incidence of ovarian cancer." (PMID 39850822, 2024). "Few specific studies have been found in linking HYDIN, a ciliary defect associated gene that encodes HYDIN axonemal central pair apparatus protein, which is involved in the transduction of Hedgehog (Hh) signal and is considered a cancer associated antigen, to ovarian cancer." (PMID 39850822, 2024). "Accordingly, the positive expression of HYDIN detected by IHC analysis in ovarian cancer tissue and tubal cilia was further investigated." (PMID 39850822, 2024). "The IHC results showed that the expression level of HYDIN protein was significantly different in ovarian tissues of ovarian cancer group (45.0%) and Healthy control group (84.0%)(P=0.000)." (PMID 39850822, 2024). "The trend of HYDIN positive expression in ovarian cancer and fallopian tube tissues in EOC group was significantly lower than that in control group." (PMID 39850822, 2024). "Thirdly, the western blotting results showed the expression level of HYDIN protein in ovarian cancer and fallopian tube tissues in EOC group was significantly lower than that in the Healthy control group, and these differences reached the level of statistical significance (P<0.05)." (PMID 39850822, 2024). "Similarly, the RT-qPCR analysis also revealed differences in the expression levels of HYDIN mRNA between the ovarian cancer groups and the Healthy control groups (P<0.05)." (PMID 39850822, 2024). "Finally, RT-qPCR and western blotting analyses were used to detect the expression of HYDIN genes in normal ovarian tissue, ovarian cancer tissue, normal fallopian tube tissue, and EOC group fallopian tube tissue." (PMID 39850822, 2024). "This study suggests that tubal ciliary loss is evident in epithelial fallopian tube carcinoma, and ciliary cells may be involved in the occurrence and development of EOC, and cilia-related gene HYDIN is expected to be a tumor marker for epithelial ovarian cancer." (PMID 39850822, 2024). "These experiments also yielded consistent results, where essentially HYDIN expression was found to be markedly absent in ovarian cancer samples and fallopian tubes of EOC group." (PMID 39850822, 2024).
autism (1 paper, 2017). Persistent deficits in social interaction and communication and interaction as well as a markedly restricted repertoire of activity and interest as well as repetitive patterns of behavior. "As an alternative approach, we sought to characterize and compare deleterious coding variation between HYDIN and HYDIN2 among 3484 probands and 2629 healthy controls from families with autism." (PMID 28279197, 2017).
bronchiectasis (1 paper, 2025). Segmental, irreversible dilation of the bronchial tree resulting in the accumulation of secretions which leads to obstruction. "Pathogenic variants in HYDIN are typically associated with a specific PCD phenotype, which in most cases is characterized by normal organ laterality, low nNO, and an increased risk of bronchiectasis." (PMID 41346656, 2025).
cervical cancer (1 paper, 2021). A primary or metastatic malignant neoplasm involving the cervix. "Mutagenesis studies of gynecological cancers have revealed that HYDIN gene undergoes frequent mutations in both ovarian and cervical cancer." (PMID 34368157, 2021).
Dyskinesia (1 paper, 2021). A movement disorder which consists of effects including diminished voluntary movements and the presence of involuntary movements. "HYDIN is a gene whose impaired function has been linked to abnormal ciliary function, dyskinesia, and brain abnormalities." (PMID 34540650, 2021).
endometrial cancer (1 paper, 2015). Primary or metastatic malignant neoplasm involving the endometrium (mucous membrane that lines the endometrial cavity).
gastric adenocarcinoma (1 paper, 2021). "Combining Kaplan–Meier survival analysis log-rank p-value, mutation coexistence pattern, and the result of random survival forest algorithm, we selected UTRN, MUC16, CCDC178, and HYDIN as candidates for an accurate prediction of survival in gastric adenocarcinoma patients." (PMID 34540650, 2021).
lower respiratory tract infections (1 paper, 2022). "Indeed, genetic defects in DNAH5, HYDIN, and TUBA1A and others result in primary cilia dyskinesia (PCD); a variety of clinical manifestations including ineffective mucociliary clearance and recurrent lower respiratory tract infections." (PMID 35169120, 2022).
neuroendocrine tumors (1 paper, 2020). "In addition, a recent study suggested that mutations in the HYDIN gene may be associated with the tumorigenesis of neuroendocrine tumors." (PMID 33732635, 2020).
cancer (7 papers, 2015 to 2025). A tumor composed of atypical neoplastic, often pleomorphic cells that invade other tissues. "We estimated the mutation profile of HYDIN across various cancers using the cBioPortal database." (PMID 37595251, 2023). "Interestingly, a novel gene HYDIN (43%, 90/209) was found highly mutated in all three cancers." (PMID 33194730, 2020). "HYDIN is considered to be a key regulator of various malignant tumors in the human body and is involved in the invasion and metastasis of cancer cells." (PMID 39850822, 2024).
tumor (5 papers, 2015 to 2026). "To further explore why patients with HYDIN mutations are more likely to benefit from ICIs treatment, we next explored tumor immunogenicity." (PMID 37595251, 2023). "It will be of interest to determine the mechanistic and phenotypic consequences of HYDIN mutations in the breast and other tumor cells." (PMID 26870154, 2015). "Particularly, tumor-associated HYDIN mutations were exclusive to G3, suggesting it may serve as a candidate biomarker for distinguishing high-grade from lower grades." (PMID 42200202, 2026). "Within the validated mutations, somatic mutations in the TRPM6, HYDIN, ENTHD1, and NDUFB10 genes were found in two or more tumor samples in the replication stage." (PMID 26870154, 2015). "Ciliated cells may be involved in the occurrence and development of EOC, and cilia-related gene HYDIN is expected to be a tumor marker for EOC." (PMID 39850822, 2024). "Five immune-related genes, SLFN13, RLTPR, HYDIN, MIR4500HG and TPRG1, were identified to be closely correlated with tumor early recurrence." (PMID 34395248, 2021). "Each gene can predict tumor early recurrence from many patients, which confirmed the utility of SLFN13, RLTPR, HYDIN, MIR4500HG and TPRG1." (PMID 34395248, 2021). "Based on Lasso regression analysis, the expressions of five immune-related genes, RLTPR, SLFN13, MIR4500HG, HYDIN and TPRG1 were closely correlated with tumor early recurrence." (PMID 34395248, 2021).
neurodevelopmental disorder (1 paper, 2021). A behavioral and cognitive disorder with onset during the developmental period that involves impaired or aberrant development of intellectual, motor, or social functions. "The HYDIN protein, associated with cilia in the brain, is critical for development of ventricles and brain; and it interacts with other genes like FOXP2 which are well known to be related to neurodevelopmental disorders such as ASD and ADHD45." (PMID 34702870, 2021).
HYDIN also shares sentences with these, for which no sentence is quoted: communicating hydrocephalus (1 paper); gynecological cancers (1); pancreatic cancer (1).